BRAF (B-Raf proto-oncogene, serine/threonine kinase)
Diseases named in the same sentence as BRAF in open-access papers (continued):
Sharing a sentence is not in itself a finding about the gene and the disease.
cancer (continued). "The ROAR trial evaluates the combination of dabrafenib (RAF-inhibitor) and trametinib (MEK-inhibitor) in subjects with rare cancers, including SBA cases characterized by a BRAF V600E mutation, an advanced stage and no standard treatment options." (PMID 35326652, 2022). "Although emerging evidence has investigated the role of BRAF, the comprehensive profiling of BRAF expression, alteration and clinical implications across various cancer types has not been reported." (PMID 35910024, 2022). "Furthermore, fusion genes involving BRAF, NTRK3, ALK, FGFR1, and ROS1, shown to activate MEK/ERK pathway in other cancers, were described." (PMID 35158933, 2022). "The sensitivity of the phenocopy signatures in mutation-negative cancer cell lines was on par with DNA alterations for EGFR, BRAF, and MAPK, and better than DNA alterations for PI3K-AKT, PARP/HRD, ERBB2, MTOR, and JAK." (PMID 36253482, 2022). "And the genetic duet of BRAF and TERT was related to advanced cancers." (PMID 36713542, 2022). "Interestingly, previous work on BRAF, EGFR, and HER2 also focused on the length of the β3/αC loop as a determinant of both kinase activation in cancer and inhibitor sensitivity." (PMID 36357385, 2022). "There is also a therapeutic need for BRAF inhibitors that are effective against non-BRAF(V600E) mutations, which are present in about 50% of BRAF-mutated NSCLC cancers." (PMID 36499382, 2022). "In these assays, two different cancer genes, BRAF and EGFR, were examined by using WT and cancer mutant plasmid DNA templates [single nucleotide (BRAF V600E and EGFR L858R) as well as deletion/insertion (EGFR Ex19Del and EGFR Ex20Ins) variants] and primers specific to cancer mutations." (PMID 36058471, 2022). "Since these modifications stimulate RAS and activate CRAF-MEK-ERK signaling, the proliferation of cancer cells is not dependent on BRAF(V600E)." (PMID 36499382, 2022). "•Proteomics for isogenic and cancer-derived models of c-MYC, AKT, BRAF, EGFR, HER2, KRAS, and MEK." (PMID 35594991, 2022). "Combination treatments with BRAF fusions and MEK inhibitors may propose a novel insight to evaluate the effectiveness of chemotherapy in cancers." (PMID 35910024, 2022). "In early-stage cancers, NNMT expression is higher in BRAF-mutated than in BRAF wild type tumors but is not affected by KRAS or PIK3CA mutation status." (PMID 35177765, 2022). "We hypothesize that our observed NRas-BRAF clusters and the NRas interactions with Grb2, NF1, and GPI in clusters could serve as novel targets for cancer therapy." (PMID 36304112, 2022). "According to preclinical studies and data in various cancers, tumors carrying a BRAF fusion are not sensitive to BRAF inhibitor therapy." (PMID 35158978, 2022). "Eight studies performed sequencing through different cancer‐related gene panels, and nine studies sequenced only predesignated genes including EGFR, KRAS proto‐oncogene (KRAS), B‐Raf proto‐oncogene (BRAF), erb‐b2 receptor tyrosine kinase 2 (ERBB2), and MET proto‐oncogene (MET)." (PMID 36000927, 2022). "In the cholangiocarcinoma without KRAS/BRAF mutations, the transcription of AHCYL1-FGFR2 did not encode a functional protein of relevance to cancer." (PMID 35578598, 2022). "In BRAF mutant PTCs, patient prognosis is significantly worse, leading to decreased patient survival rates as well as increased LNM, increased extrathyroidal extension, and more advanced cancer stage." (PMID 36009596, 2022). "Vitamin C gets inside these cancer cells and disrupts the expression of KRAS or BRAF genes." (PMID 36245983, 2022). "In contrast, BRAF inhibitors, e.g., PLX4032, have been approved for the treatment of some cancers." (PMID 35585049, 2022). "A similar process has been reported with targeted BRAF inhibition in BRAF mutant cancers, where deactivation of the negative feedback mechanism induces EGFR-mediated activation of RAS." (PMID 36189421, 2022).
cancer (continued). "In addition, kinases are ideal targets for cancer therapy; several inhibitors against kinases, such as ALK and BRAF, have been used to treat cancers with fused genes." (PMID 33557176, 2021). "Indeed, the majority of solid tumors are explicitly characterized by their mutations in the RAS/RAF/MEK/ERK genes, wherein highly selective small molecule inhibitors of BRAF and MEK1/2 are currently used for cancer therapy." (PMID 34685488, 2021). "In 2020, the FDA granted an expanded access program for the ERK inhibitor ulixertinib (BVD-523) for the treatment of cancer patients with abnormal MAPK pathways, including but not limited to those involving KRAS, NRAS, HRAS, BRAF, MEK, and ERK mutations." (PMID 34607583, 2021). "Data for CT of other anti-cancer TT studied in elderly have been reviewed (anti-angiogenic treatment, anti EGFR, M-TOR inhibitors, BRAF and MEK inhibitors, C-KIT inhibitors, HER2 targeted therapies, tyrosine kinase inhibitors, or ALK inhibitors) and showed similar results that for younger patients." (PMID 34207200, 2021). "With these advances, novel targeted therapies, including several kinase inhibitors (KI) such as BRAF inhibitors (BRAFi), EGFR inhibitors (EGFRi) and CDK4/6 inhibitors, have been introduced in the clinics for the treatment of a variety of cancer entities." (PMID 34298736, 2021). "Moreover, the alteration in expression levels of other molecules such, c-MET, RAS/BRAF, EGFR/ERBB2 which are involved downstream, affect cancer cell proliferation and development." (PMID 33777535, 2021). "Problem 1 asked participants to predict molecules that bound the RETM955T-associated cancer pro-targets RET[M918T], BRAF, SRC, S6K, and did not bind the anti-targets MKNK1, TTK, ERK8, PDK1, and PAK3." (PMID 34520464, 2021). "Therefore, components and regulators of the ERK pathway are considered potential therapeutic targets for cancer, and inhibitors of this pathway, including some MEK and BRAF inhibitors, are already being used in the clinic." (PMID 34685488, 2021). "In 119 538 nonredundant cancer samples, class 1 BRAF alterations and BRAF fusions were found to be mutually exclusive to alterations of RAS or RAS regulatory genes (odds ratio range 0.03-0.13 and 0.03-0.73 respectively), confirming their RAS independency." (PMID 33507258, 2021). "BRAF is a serine-threonine kinase just downstream of EGFR/KRAS that activates the MEK/extracellular signal-regulated kinase (ERK) signalling cascade through its phosphorylation and then promotes cancer cell proliferation." (PMID 34663410, 2021). "Nonetheless, it will be important in future studies to confirm this function of LRP6 in a more relevant model of human cancer such as patient-derived CRC organoids (e.g., with or without BRAF mutation)." (PMID 34359960, 2021). "For example, initially during early tumorigenesis, BRAF-driven lung tumor formation was accelerated upon Atg7 deletion, but later, these tumors slowed their growth and failed to transition from benign to malignant tumors." (PMID 34298710, 2021). "In this cross-sectional study of genomic data analysis with more than 11 9000 cancer samples, it was found that current BRAF alteration classification does not accurately represent in vivo RAS dependency for non-V600 alterations." (PMID 33507258, 2021). "A phase I clinical trial combining the BRAF inhibitor vemurafenib and everolimus showed generally favorable results for patients with advanced cancers, along with no excessive toxicity." (PMID 34831420, 2021). "Similar to that observed for TCGA’s BRAF V600E positive samples, negative BL samples had an overall higher expression of cancer-related genes and pathways when compared to negative RL, particularly the PI3K, JAK/STAT, and MAPK pathways." (PMID 34680332, 2021).
cancer (continued). "Unlike drug resistance that occurs in EGFR mutation-driven cancers or BCR-Abl-induced leukemia, secondary mutations such as gate-keeper mutations that cause drug resistance are rare in BRAF(V600E)-driven cancers." (PMID 35582307, 2021). "Kinase inhibitors have shown great potential as a TNBC regimen due to their activity as antitumor and antiangiogenic therapies by targeting genes and pathways that play a role in cancer development and proliferation, like targeting EGFR, RON, MET, mTOR, BRAF, MEK, Src, and Bcr/Abl." (PMID 34944904, 2021). "If the BRAF gene status did not match in the cancers and metastases, an increase in the level of mTOR mRNA, NFkBp65; VHL; ERα was observed in 32.8; 67.3; 56.0; 1.5 times." (PMID 34319022, 2021). "This revealed that the NKX2-1 protein is needed to initiate the formation of cancer cells but is not required for the growth of already established BRAF-driven tumors." (PMID 33821796, 2021). "Pan-inhibitors that inhibit b-RAF proto-oncogene (BRAF) and c-RAF proto-oncogene (CRAF) as well as not activating the MAPK pathway in cancers harboring KRAS mutations are being generated and show in vitro promising results." (PMID 33801965, 2021). "In summary, our results demonstrated that AIM2 expression was low in BRAF-mutant CRC, and restoration AIM2 expression in BRAF-mutant CRC cells could inhibit cancer cell growth in a caspase-1-dependent manner." (PMID 33842454, 2021). "We observed that most of the cancer cells with the wild types of both KRAS and BRAF still exhibit resistance to SHP2 inhibition, which cannot be fully explained by the p-SHP2 levels, indicating an unknown mechanism for the resistance." (PMID 34790119, 2021). "The top amplified cancer genes were KRAS, CDK4, BRAF, IL6, TLK2 and MITF." (PMID 34313788, 2021). "The transcription of YAP1 and TAZ in the Hippo signaling pathway plays a critical role in mediating the resistance of major cancer treatment drugs, and is considered to play a major driving role in the development of resistance of BRAF- and KRAS- mutant cancer cells." (PMID 33996543, 2021). "Interestingly, all significant results targeted known cancer driver genes such as EGFR, HER2, PIK3CA, and BRAF." (PMID 33872312, 2021). "Several actionable cancer genes such as EGFR, ALK, ROS1, BRAF have been identified, for which specific targeted therapies exist; however, >40% of patients’ tumors do not have alterations in actionable genes thus excluding for these patients the possibility of being treated with a targeted therapy." (PMID 34164404, 2021). "The paradox breakers, PLX7904 and PLX8394, are effective at treating both BRAF-mutant and BRAF-inhibitor-resistant cancers without inducing RAF dimerisation and paradoxical activation of the ERK1/2 pathway." (PMID 33367512, 2021). "Stratified with stage, improved cancer-specific survival (CSS) has been observed in CIMP positive CRC regardless of MSI status and BRAF mutation." (PMID 34381313, 2021). "Both AMG-510 and vemurafenib selectively and potently abolished the growth of the K-RasG12C- and BRAF-V600E-mutant cancer cell 3D spheroids, respectively, with basically no activity against other cancer cell spheroids." (PMID 34307350, 2021).
cancer (continued). "The constitutive negative charge within the BRAF NtA region leaves the protein ‘primed’ for dimerisation, and able to be activated by single site phosphorylation or single point mutations; this may explain why BRAF mutations are far more common in cancer than ARAF or CRAF mutations." (PMID 33367512, 2021). "Importantly, the inhibition of cell growth was observed even under a full growth condition for these cancer cell lines; these cells were indeed addicted to the expression of the KRAS or BRAF oncogene for their cell growth." (PMID 33793658, 2021). "In addition, several case series have published good tolerability and response to this combination and another phase-2 trial, VE-BASKET, demonstrated single agent efficacy of the BRAF inhibitor, vemurafenib, in BRAFV600E mutant cancers." (PMID 32932925, 2020). "A large-scale survey of cancer genomic and therapeutic databases has identified five candidate genes, namely PIK3CA, BRAF, NF1, NRAS, and PTEN, the targeting of which could be suitable for combination therapy with immunotherapy." (PMID 32483262, 2020). "Thus, BRAF V600E and RET/PTC confer > 99% probability of cancer, which is consistent with the literature." (PMID 32781560, 2020). "Although the BRAF V600E-specific antibody (clone VE1) has been widely used in BRAF V600E detection, false-positive and false-negative results are frequently observed in various types of cancers, including lung cancer." (PMID 33037234, 2020). "These genes include very well-known cancer related oncogenes such as BRAF, ERBB2, AKT1 and PIK3CA with the genes which are not listed in the cancer gene census list of the COSMIC database." (PMID 32998690, 2020). "Clinically effective chemotherapy for RAS-mutant cancers, unlike BRAF V600E-mutant cancers, remains to be developed due to their intrinsic resistance." (PMID 33060766, 2020). "The function of RAF as a prominent cancer driver was not established until the discovery of BRAF(V600E) in 2002." (PMID 31941155, 2020). "In oncogene-addicted cancer cells, metabolic reprogramming to OXPHOS was observed to be involved in the mechanism of chemoresistance towards targeted therapy with the EGFR inhibitor gefitinib and the BRAF inhibitor vemurafenib in vitro." (PMID 32610612, 2020). "In summary, our study found that DNA methylations at seven CpG sites on CIMP-related genes were strongly associated with CRC prognosis independent of cancer stage, MSI status, BRAF mutation status, and other important factors that affect the outcome of CRC." (PMID 31340858, 2019). "In fact, parental SW48 and LIM1215 cancer cells were significantly sensitive to cetuximab, panitumumab, SYM004 and MM-151 antibodies inducing growth inhibition, as expected being “quadruple wild type” for KRAS, BRAF, NRAS and PIK3CA genes." (PMID 31164152, 2019). "However, multiple published studies have used different genes (e.g., KRAS, BRAF, APP, ACTB, GAPDH, 16s rRNA, ALU, LINE 1) as biomarkers to determine cfDI in various cancers." (PMID 31620364, 2019). "Relatively non-toxic gene targeted therapies for PIK3CA and BRAF are FDA-approved or in advanced trials for some cancers." (PMID 31711466, 2019). "This suggests either that osimertinib has eliminated the T790M-positive clones or that the cancer cells themselves have lost this osimertinib-target, thereby switching from T790M as acquired driver to another acquired driver such as RTK- or BRAF-fusion proteins." (PMID 31266248, 2019). "Preclinical study of trametinib showed efficacy against cancer cells with either BRAF or RAS mutations and even on cancer cells with neither BRAF nor RAS mutations; therefore, cancers without BRAF mutations are included in clinical trials of trametinib." (PMID 30899200, 2019). "In this study, BRAF V600E, RETPTC1 rearrangement, and TERT promoter mutations were found to be associated with more aggressive cancers when compared to malignancies without one of these mutations." (PMID 31623671, 2019).
cancer (continued). "For instance, BRAF is targeted by 2 viral proteins (NS2_HCV and E7_HPV) and it has 4 chemotherapy drugs that are used in different non-virally induced cancers." (PMID 31803618, 2019). "A first important finding of our analysis was that CRbC mainly included BRAF mutant/MSS cancers without CIMP." (PMID 31455041, 2019). "By contrast, PDMC only comprised BRAF mutant/MSI and CIMP cancers." (PMID 31455041, 2019). "Interestingly, the signal of the phosphopeptides was higher in the presence of the mutant form of bRAF (bRAFV600E), again suggesting a potentially important role of TRF1 modification by bRAF in cancer." (PMID 31273934, 2019). "This uncoupling results in constitutive activation of BRAF that is independent of upstream stimuli for growth and proliferation in cancer." (PMID 31426419, 2019). "Therefore, this demonstrates that CIMP is prevalent in all BRAF mutant cancers of the serrated pathway, but at a higher frequency in MSI (70–80%) than MSS (60%) cancers." (PMID 30598662, 2018). "Although the presence of CIMP has correlated with worse survival in MSS cancers compared to those without CIMP, the negative effect of the BRAF mutation far exceeded that of CIMP which suggested that the BRAF mutation was acting independently of CIMP." (PMID 30598662, 2018). "The remaining BRAF mutant cancers that do not methylate MLH1 to develop MSI stay as microsatellite stable (MSS)." (PMID 30598662, 2018). "The delineation of the exact mechanistic details downstream of BRAF/AXL and upstream of transcription factors that control RIPK3 transcription is likely to be of importance to our understanding of cancer escape from necroptosis and will be elucidated in future studies." (PMID 30157175, 2018). "This review will explore our current understanding of BRAF mutant cancers with respect to presence or absence of MSI." (PMID 30598662, 2018). "In contrast to some other hematologic malignancies [e.g., hairy cell leukemia (BRAF) and Waldenström’s macroglobulinemia (MYD88)], MMs do not harbor any specific or unifying mutation(s)." (PMID 30021955, 2018). "This latter BRAF mutant/MSS cancer subgroup has not been as well studied, but is known to particularly associate with a poor patient outcome." (PMID 30598662, 2018). "That fair amount of sporadic cancers may still demonstrate some levels of MSI having other genetic changes that correspond more to the final presentation like CIN, CIMP and BRAF status." (PMID 28451866, 2018). "Due to the decreased binding with BRAF, the activation of ERK, and the similar cancer transformation properties to KRAS G12V, we wanted to test whether RHEB Y35N transforms cells through the RAF/MEK/ERK pathway." (PMID 29320991, 2018). "The first CFC mouse model expresses low levels of the oncogenic BRAF V600E protein (B-Raf+/LSLV600E mutants), a constitutively BRAF active form linked to cancer, but not reported in CFC patients." (PMID 29590634, 2018). "A research in 2011 indicate that oncogenes like KRAS, MYC and BRAF can promote the expression of NRF2 to degrade ROS to make a more reduced intercellular environment, therefore, protects cancer cell from oxidative stress and promote cell proliferation and tumorigenecity." (PMID 29416692, 2018). "The reported incidence of BRAF mutant lesions that develop MSI ranges from 46% to 75%, and these BRAF mutant/MSI cancers have been well characterized to show typical clinicopathological features such as a predilection for elderly females and a proximal location." (PMID 30598662, 2018). "No cancer-associated EGFR gene mutation or copy-number variation, nor any KRAS, BRAF, NRAS hotspot mutations were found in any microdissected area." (PMID 29492209, 2018).